MLC1 (modulator of VRAC current 1)
Diseases named in the same sentence as MLC1 in open-access papers (continued):
Sharing a sentence is not in itself a finding about the gene and the disease.
injury (1 paper, 2024). Damage inflicted on the body as the direct or indirect result of an external force, with or without disruption of structural continuity. "Moreover, MMP-2 contributes to acute cardiac dysfunction through the degradation of intracellular contractile machinery proteins, such as troponin I (TnI), titin, myosin light chains 1 and 2 (MLC1 and 2) in oxidative-stress-induced-heart injury." (PMID 38540247, 2024).
intellectual disabilities (1 paper, 2020). "There was also overlap for genes involved in intellectual disabilities, including AFF2, AIFM1, CA8, EEF1A2, MLC1, and XYLT1, but statistically the overlap is not significant." (PMID 32393163, 2020).
prion disease (1 paper, 2022). A transmissible disease that is caused by a protein that is able to induce abnormal folding of normal cellular proteins, leading to characteristic spongiform brain changes, which are associated with neuronal loss without an inflammatory response. "Interestingly, increased expression of MLC1 at the perivascular astrocyte end-feet has been observed in the brain of patients affected by AD, MS, and also prion disease, which might indicate an attempt to ameliorate these pathological processes by increased MLC1 expression in activated astrocytes." (PMID 36078064, 2022).
Sepsis (1 paper, 2019). Sepsis is defined as life-threatening organ dysfunction caused by a dysregulated host response to infection. "MLC1(1f), MLC1(3f), and MLC1(s) decreased after 48 and 96 h of sepsis." (PMID 31660704, 2019). "MLC1(1f), MLC1(3f), and MLC1(s) decreased in the TA after 24, 48, and 96 h of sepsis." (PMID 31660704, 2019). "MLC1(1f), MLC1(3f), MLC1(s), and MLC2(f) protein levels decreased after 24, 48, and 96 h of sepsis." (PMID 31660704, 2019).
cancer (8 papers, 2015 to 2026). A tumor composed of atypical neoplastic, often pleomorphic cells that invade other tissues. "It is often overexpressed in pan-cancer settings, associated with poor outcomes.MLC1, located on chromosome 22, is typically associated with the white matter of the central nervous system and is highly expressed in vascular astrocytes." (PMID 39558952, 2024). "These included homozygous variants calls in genes related to cancer (BRCA1, APC, MEN1), congenital malformation syndromes (TCOF1), metabolic deficiencies (FBP1, HEXA), and neurological diseases (FUS, MLC1, DMD)." (PMID 26547235, 2015). "Interestingly, certain repressed genes like B4GALT2, ELANE, CTSG, MLC1, NMP3, and SLC43A3 act as cancer suppressors, inhibiting malignant features and cancer development." (PMID 40986633, 2025).
tumor (3 papers, 2020 to 2024). "MLC1 expression is negatively correlated with tumor metastasis and has an anti-tumor effect." (PMID 39558952, 2024).
neurodevelopmental disorder (2 papers, 2020 to 2021). A behavioral and cognitive disorder with onset during the developmental period that involves impaired or aberrant development of intellectual, motor, or social functions. "Since mutations in MLC1 cause the neurodevelopmental disorder MLC, it is possible that alterations in additional PA-expressed genes are linked to BBB defects in other pathologies." (PMID 33031376, 2020).
neurological diseases (2 papers, 2015 to 2021). "Mutations in the MLC1 protein can cause a neurological disorder named MLC disease." (PMID 34847774, 2021).
infection (1 paper, 2019). The state of being infected such as from the introduction of a foreign agent such as serum, vaccine, antigenic substance or organism. "Infection with shMlc1 virus significantly reduced the endogenous Mlc1 expression level in the primary astrocyte culture, which indicated that shMlc1 is useful to silence Mlc1." (PMID 31888684, 2019).
MLC1 also shares sentences with these, for which no sentence is quoted: breast cancer (2 papers); glioblastoma (2); glioma (2); melanoma (2); myocardial ischemia (2); neurodegenerative disease (2); Alexander disease (1); asphyxia (1); Ataxia (1); bladder cancer (1); brain inflammation (1); cardiomyopathy (1); cognitive decline (1); congenital malformation syndromes (1); developmental delay (1); diabetes insipidus (1); leiomyosarcoma (1); Lissencephaly (1); necrosis (1); ovarian carcinoma (1); pulmonary edema (1); Shock (1); teratospermia (1).